CD4 (CD4 molecule)
Diseases named in the same sentence as CD4 in open-access papers (continued):
Sharing a sentence is not in itself a finding about the gene and the disease.
asthma (continued). "Regulatory T cells (Treg) have a suppressive effect on other CD4+ T effector cells and may play a role in regulating Th2 function in asthma." (PMID 35185864, 2021). "Curcumin downregulated IL-4 and IL-5 levels but upregulated IFN-γ in the BALF of a murine model of asthma and attenuated allergic airway inflammation by modifying the balance of CD4‏+ CD25+ regulatory T cells (Tregs)/T-helper (Th) in ovalbumin (OVA)-sensitized mice dose-dependently." (PMID 34804178, 2021). "Ovalbumin-induced asthma in CD4-Cre:Spry2f/f mice had similarly reduced lung inflammation." (PMID 33684096, 2021). "Although CD4+ T cells and other immune cells play key roles in the pathogenesis of asthma, several studies have reported a relationship between the host microbiota and asthma." (PMID 34769255, 2021). "In addition, we discuss the role of the bacterial microbiota in the induction of asthma and its effect on CD4+ T cells in asthma." (PMID 34769255, 2021). "Meanwhile, the effect of miRNA-221-5p on Th17/Treg Ratio in asthma, whether miRNA-221-5p regulates CD4 T cell in cancer model, and we will analyze the anti-cancer or pro-cancer effects of miRNA-221-5p on tumour immune in further research." (PMID 34863307, 2021). "However, cellular source for FKBP51 as it relates to asthma severity has never been described and herein, we identify FKBP51 expression in CD4+ T-lymphocytes as a possible mediator of steroid resistance in obese asthma." (PMID 34721414, 2021). "CD4+ T cells play important roles in determining the asthma phenotype." (PMID 34769255, 2021). "CD4+CRTH2+CCR6+ cells secrete IL-17, IL-4 and IL-13, leading to the infiltration neutrophils and eosinophils, which is responsible for chronic inflammation associated with asthma." (PMID 34090369, 2021). "Th2 cytokines (such as interleukin (IL)-4, IL-5, and IL-13) are produced by CD4+ T cells and are believed to play a key role in asthma pathogenesis by promoting recruitment and activation of mast cells and eosinophils, which are the primary effector cells in the allergic response." (PMID 34356851, 2021). "Moreover, circulation CD4+CCR6+CRTh2+ memory Th2 cells, which have certain lung tissue specificity, was increased in asthma diagnosed children and was risk factor for the outcome of asthma diagnosis." (PMID 34090369, 2021). "APC-dependent allergen priming of CD4+ T cells decides the endotype and phenotype of asthma." (PMID 34414402, 2021). "The observed differences in the frequencies of Treg cell subtypes associated with the susceptibility of the animals to experimental asthma suggest that CD4+CD25+Foxp3+ and IL-10-producing CD4+ Treg cells may play different roles in asthma control." (PMID 34924814, 2021). "This led us to conjecture that GITRL might promote the development of asthma by modulating the differentiation of CD4+ T cells." (PMID 33557842, 2021). "The increase of Treg (CD4+CD25+FOXP3+) after PMBL® treatment may be the possible mechanism that prevents asthma exacerbations and reduces the severity of this disease." (PMID 33472687, 2021). "Therefore, CD4+CD25+Foxp3+ TReg cells are considered as one kind of target cells for allergen-specific immunotherapy in asthma." (PMID 34630778, 2021). "A recent study showed that lncRNA-MEG3 could competitively sponge miR-17 in the CD4+ T cells of asthma patients to regulate the expression of RORγt and ultimately affect the balance of Treg/Th17." (PMID 34635022, 2021). "In comparing the incidence rate of autophagic activity in CD4+ T-cell between the control and DXM undertreatment groups, it was concluded that DXM could induce autophagy in the CD4+ T lymphocytes of asthma patients." (PMID 34468179, 2021). "This suggests CD4+ T-lymphocyte FKBP51 expression may represent a novel therapeutic target of particular relevance in obese individuals with asthma." (PMID 34721414, 2021). "Taken together, we speculated that CD4 might play a role in asthma by affecting immune-related biological functions." (PMID 34285702, 2021).
asthma (continued). "Collectively, these results confirm the conclusion that GITRL on DCs may promote asthma by modulating CD4+ T cell differentiation and disturbing the balance of Th1/Th2 and Th17/Treg cells." (PMID 33557842, 2021). "Notably, no statistically significant differential gene expression was detected when comparing other asthma cells or biopsies with control samples, including CD4+, CD8+, CD14+, CD15+, CD19+ cells, platelets (low expression), transverse colon or rectum biopsy." (PMID 34332619, 2021). "The present study implicates that altered SL acyl chain length may contribute to the pathophysiological mechanism of CD4+ T cell-mediated inflammatory diseases such as asthma." (PMID 33800208, 2021). "Therefore, during an asthma attack, CD4+ T cells shift to both Th2 and Th17 cells under the influence of certain factors and inhibit the formation of Tregs." (PMID 32834826, 2020). "Additionally, studies have demonstrated that CD4+ Th2 cells, which play critical roles in asthma pathogenesis, are directly regulated by IL-10 during allergic airway inflammation." (PMID 33287119, 2020). "Similar to observations found in murine studies, 7P diminished the differentiation of human naïve CD4+ T cells in peripheral blood to Th9 cells, further indicating that 7P may be a good candidate for reducing IL-9 production in asthma." (PMID 32258172, 2020). "In addition, some studies have shown that DCs play a major role in the pathogenesis of asthma because IL-23, which is a Th17-induction factor, is usually produced by DCs and macrophages, and is sufficient to induce IL-17A production in naïve CD4+ T cells." (PMID 32410846, 2020). "In addition, CD4+ T cells of asthma patients and healthy controls were stimulated with WNT5A and changes in gene transcription assessed by RNA-seq." (PMID 32317758, 2020). "CD81 expression in CD4+ T cells is induced by Th9-inducing factors during asthma attacks." (PMID 32258172, 2020). "However, dectin-1 signaling was also shown to be associated with CD4+ T cell production of IL-4, IL-13, and IFN-γ to a lesser extent, suggesting an interplay between Th2 and Th17 responses in fungi induced asthma." (PMID 33324573, 2020). "To directly follow up from these results, we additionally treated CD4+ T cells of asthma patients and healthy controls with WNT5A, and used bulk RNA-seq to reveal transcriptional changes and identify WNT5A induced cytokines that could mediate this." (PMID 32317758, 2020). "In addition to presenting antigens and inducing immune responses and asthma, airway DCs also induce CD4+ T cells to differentiate into Tregs and thus induce immune tolerance, preventing the onset of an asthma episode." (PMID 32834826, 2020). "The transcriptional profile of human CRTH2+ CD4+ T cells was studied in the context of asthma, where it was found that IL17RB, which encodes for the IL-25R, had a ~3.35-fold increase in transcripts in asthma patients compared to healthy controls." (PMID 33374787, 2020). "Early studies in patients with mild asthma have shown that CD4+ T cells favour Th2 type immune responses in BALF, lung tissue, and blood, and secrete large amounts of cytokines, such as IL‐4, IL‐5, IL‐13 and IL‐9, while Th1‐type cytokines such as IFN‐γ, IL‐2 and IL‐12 are reduced." (PMID 33124760, 2020). "Despite hidden linkages between PVT1 and airway remodeling/inflammation, it remained ambiguous whether PVT1 indeed disrupted normal activity of ASMC and CD4+ T cell by sponging protective miRNAs in asthma." (PMID 33223504, 2020). "In addition, RP11-13A1.1 was significantly and differentially upregulated in CD4+ T-cells of obese children with asthma compared with normal-weight children." (PMID 32614437, 2020). "CD4+ T cell dysregulation or imbalance can lead to autoimmunity, asthma, or prolonged infection." (PMID 33424845, 2020).
asthma (continued). "Herein, we studied tissue-specific DEGs in multiple datasets originating from independent studies using multiple asthma tissue/ cell sample types (bronchial epithelium, peripheral blood, CD4+ and CD8+ lymphocytes, nasal epithelial, induced sputum, airway fibroblast and airway macrophages)." (PMID 32900903, 2020). "Although various cellular functions of ORMDL3 have been characterized, its precise mechanistic role in altering CD4+ T cell function and enhancing asthma susceptibility has not been resolved." (PMID 33424845, 2020). "One of the key features of asthma is skewing of CD4+ cells toward Th2 responses." (PMID 32292999, 2020). "Our previous findings suggest that CD4+CRTh2+ T cells numbers are increased in patients with severe asthma compared to mild/moderate disease and may be increased primarily in patients with frequent asthma exacerbations." (PMID 31168305, 2019). "Top 20 lncRNAs in CD4+ T cells between asthma and control groups." (PMID 31231429, 2019). "Another similar study showed that AS-IV also could attenuate allergic inflammation by regulation Th1/Th2 cytokine and enhancement CD4+CD25+Foxp3+ T cells in ovalbumin-induced asthma." (PMID 30909474, 2019). "Top 20 mRNAs in CD4+ T cells between asthma and control groups." (PMID 31231429, 2019). "Moreover, our results highlighted the potential internal adjustment correlations between the differentially expressed lncRNAs and mRNAs in CD4+ T cells between the asthma and control groups." (PMID 31231429, 2019). "Therefore, reduction of CD126 expression in monocytes, neutrophils, and CD4+ cells from moderate-severe patients highlights the role of IL-6 trans-signalling in asthma severity." (PMID 31101830, 2019). "Asthma severity is also influencing CD126 levels on CD4+ T cells, neutrophils and monocytes." (PMID 31101830, 2019). "The lncRNA fantom3_9230106C11 was significantly reduced in CD4+ T cells of asthma." (PMID 31231429, 2019). "CD4+ T cells participate in the pathogenesis of chronic inflammation in asthma." (PMID 31496071, 2019). "Most research in asthma has been focused on the allergic phenotype and CD4+ T cells." (PMID 31101830, 2019). "This study provided the first evidence for different expression of lncRNAs of CD4+T cells in asthma and may serve as a template for further, larger functional in-depth analyses regarding asthma molecular lncRNAs." (PMID 31231429, 2019). "Thus, a TSLP-DC-OX40L pathway was formed and promoted airway inflammation and asthma pathogenesis by increasing inflammatory cytokines and decreasing CD4 + CD25 + Treg cells." (PMID 30890137, 2019). "However, lncRNA fantom3_9230106C11 was in accordance with sequencing data, which was significantly decreased in the asthma CD4+ T cells." (PMID 31231429, 2019). "In the lncRNA profile analysis, the roles of a wide range of lncRNAs with varied expression in asthma CD4+ T cells were largely unknown." (PMID 31231429, 2019). "However, we found that the frequency of α4+ CD4+ T cells significantly correlated with asthma severity, as assessed with the ACT scores." (PMID 29507584, 2018). "In addition, the percentage of circulating CCR4+CD45RA−CD45RO+CCR7+ CD4+ T cells in patients correlated with asthma severity, as measured with % predicted FEV1 scores." (PMID 29507584, 2018). "Accordingly, the frequency of CCR4+CCR7+ memory CD4+ T cells correlated with asthma severity." (PMID 29507584, 2018). "The inverse correlation between the frequency of CCR4+ CD4+ Tcm cells and asthma severity further support that CCR4+ CD4+ Tcm cells could play an important role in the pathogenesis of atopic asthma." (PMID 29507584, 2018). "The release of pro inflammatory mediators (e.g., histamine, reactive oxygen species) trigger an inflammatory response in which mast cells, basophils, eosinophils, and CD4+ Th2 lymphocytes help to induce the signs and symptoms characteristic of full-blown asthma (bronchial hyper-reactivity)." (PMID 30233389, 2018).
asthma (continued). "It is therefore possible that such long-lived CD4+ Tcm cells found in the blood of asthma patients could play an important role in the chronic inflammation in the lower airway in response to a variety of allergens that are intermittently available year-round." (PMID 29507584, 2018). "Although little is known about epigenetic regulation in neutrophils-dominant asthma, in our study we report that MBD2 expression in splenic CD4+ T cells and lungs from neutrophils-dominant asthma mice was significantly higher compared to conventional asthma mice and the control group." (PMID 30150897, 2018). "In addition, the percentage of CD4+ T cells expressing surface CTLA-4 inversely correlates with asthma severity, as determined by the ACT scores." (PMID 29507584, 2018). "The increase of CCR4+ CD4+ T cells in asthma patients has been previously reported." (PMID 29507584, 2018). "We next investigated whether the increase of circulating CCR4+ CD4+ T cells in patients could be a feature of asthma subtypes." (PMID 29507584, 2018). "Together, the data indicates that RSV infection could apparently increase C5a and C5aR expression in the pathogenesis of RSV-infected asthma mice, meanwhile C5aRA prevents some of the CD4+T cells immune changes that are induced by RSV." (PMID 29123203, 2017). "Some studies have suggested that other CD4+ T cell subsets may play a role in asthma, including Th17 and Treg cells." (PMID 28674387, 2017). "Up to now, there is no research focusing on the mechanism of C5a-C5aR mediated by RSV infection, meanwhile this project was the first time to report RSV infection exacerbates asthma pathogenesis via activating C5a-C5aR and then regulating CD4+T cells immune response." (PMID 29123203, 2017). "Notably, asthma, atopic dermatitis and allergy were mapped to CD4+ T helper cells, whereas alopecia areata and juvenile idiopathic arthritis were mapped to CD4+ CD25+ regulatory T cells." (PMID 28302177, 2017). "Assuming the diverse functions of Th1, Th2, Th17 and Treg cells in RSV infection and asthma, we speculated that these CD4+T cells also contribute to RSV-induced asthma exacerbation." (PMID 29123203, 2017). "Furthermore, cell suspensions from the lung were stained with antibodies specific for CD4 and the master transcription factors for T-bet, Gata-3, RORγt, and Foxp3 to better understand the roles of CD4+ T subsets in the pathogenesis of asthma." (PMID 29162668, 2017). "However, little is known about that epigenetic regulation of MBD2 in both immunological pathogenesis of experimental severe asthma and CD4+ T cell differentiation." (PMID 28808358, 2017). "Although complement might regulate CD4+T cells immune responses in asthma model, this regulation existed in RSV-induced asthma model remains incompletely characterrized." (PMID 29123203, 2017). "CD4+/CD25+ regulatory T cells suppress pathogenic Th2 responses in Th2-mediated allergic inflammatory diseases; thus, induction of allergen-specific regulatory T cells has recently been considered to be an attractive strategy for asthma therapy." (PMID 29062168, 2017). "A ChIP-Seq study of H3K4me2 in naïve and memory CD4+ T cells obtained from 12 asthma patients and 12 healthy controls found that H3K4me2-marked enhancers were associated with both asthma susceptibility and Th2 cell type, and that asthma GWAS SNPs were enriched in the Th2 enhancers." (PMID 28774304, 2017). "In addition to reduced type 2 cytokine protein levels in OVA‐driven asthma, diminished mRNA expression levels of Il‐5, Il‐13, and Il‐4 were observed in CD4‐enriched lung cells from LXRα−/−β−/− mice." (PMID 27621817, 2016). "Differential network analysis of HDM-induced CD4 T cell responses in sensitized atopics with or without asthma unveiled a cohort of asthma-associated genes that escaped detection by more conventional data analysis techniques." (PMID 26922672, 2016).
asthma (continued). "It has been shown that pharmacologic HO-1 induction mediates the anti-inflammatory effects in several models of inflammatory diseases, including asthma and transplantation; however, the interaction of HO-1-expressing DCs and CD4+CD25+ Tregs remains unclear." (PMID 28033400, 2016). "Recent studies have shown that CD4 cells from steroid insensitive asthma patients release more IL-17 than cells from steroid sensitive patients and that, unlike TH2 cells, IL-17 producing BAL T-cells from severe asthma patients are insensitive to corticosteroid-induced cell death." (PMID 27716212, 2016). "It is known that eosinophilic inflammation in asthma is controlled by CD4+ lymphocytes." (PMID 27660519, 2016). "In asthma, there are a number of studies both in patients and in animal models that demonstrate a potential role of IL-10 regulating inflammation in the airways, where the main source is CD4+ CD25+ T-lymphocytes." (PMID 27795621, 2016). "In parallel, we constructed the coexpression network underlying CD4 T cell responses in HDM-sensitized atopics without asthma." (PMID 26922672, 2016). "At the FGFR2 gene expression level, associations were identified with CD4+/CD8+ T-cell responses in severe asthma, dendritic cell response to Chlamydia pneumonia lung infection and PGE EP3 induced asthma (GEOprofile datasets GSE2276, GSE31773, GSE470, GSE12806)." (PMID 26999364, 2016). "CD4 T cell responses are themselves heterogeneous, comprising multiple subsets that can either promote (Th1, Th2, Th9, Th17) or negate (Treg, Tr1) the airway inflammatory processes that underpin asthma." (PMID 26922672, 2016). "Interestingly, CD4+ T cells with the same phenotype were shown to inhibit the development of hyper-reactivity in an mouse model for asthma." (PMID 26866695, 2016). "Finally, we employed upstream regulator analysis to identify negative regulators of HDM-driven CD4 T cell responses in sensitized atopics with asthma." (PMID 26922672, 2016). "In contrast, regulatory T cells (Treg cells, a CD4+CD25+FOXP3+ subset) have inhibitory effects on asthma airway inflammation, inhibiting the proliferation of other T cells; it is believed they are mediated by cytokines such as tumor growth factor beta (TGF-β) and IL-10." (PMID 26565810, 2015). "Previously, we showed that Notch signal pathway regulates the proliferation and differentiation of CD4+ T lymphocytes in a mouse model of asthma, indicating that Notch may be a potential target for treating asthma." (PMID 26339131, 2015). "We used ovalbumin (OVA)-based mouse models of asthma and primary CD4+ T cells." (PMID 26169874, 2015). "The sex differences in IFN-γ production by CD8+ T cells and IFN-γ receptor expression on CD4+ T cells may be a necessary and sufficient for female-dominant IL-4 production in asthma." (PMID 26488300, 2015). "IL-17-producing (Th17) CD4+ Th cells are important players in asthma pathogenesis." (PMID 26339131, 2015). "It contrasts with evidence of T cell activation on presentation during severe asthma attacks; the same study found that blood CD4+ T cells of five subjects hospitalized for AE-COPD showed increased expression of HLA-DR, which we did not measure, but not of CD25, in agreement with our data." (PMID 26243260, 2015). "In this current study we sought to compare DNA methylation levels at highly conserved (between human and mouse) CpG sites in the IFNγ gene promoter region (CpG -186 and -54) between CD4+ T lymphocytes and buccal cells in a select cohort of allergic-sensitized children and adults with asthma." (PMID 24891923, 2014). "Interestingly, approximately half of the CD4+IL-17+ cells in our study expressed INF-γ+ and the percentage of these CD4+IL-17+INF-γ+ cells was significantly increased in asthma (P = 0.047)." (PMID 25132806, 2014). "Furthermore, many autoimmune and allergic diseases are CD4+ T-cell dependent, such as asthma (Vock et." (PMID 25051576, 2014).